IFNG (interferon gamma)
Diseases named in the same sentence as IFNG in open-access papers (continued):
Sharing a sentence is not in itself a finding about the gene and the disease.
arbovirus infection (1 paper, 2021). A viral infection that is transmitted by an arthropod. "In addition, infected monocytes, macrophages, and dendritic cells produce high levels of neopterin, which is a biomarker of the immune system induced by the production of interferon-gamma (IFN-γ) and synthesized by T lymphocytes and NK cells that occurs in arbovirus infection." (PMID 34959581, 2021).
arterial disorder (1 paper, 2016). An impairment of the structure or function of the blood vessels which carry blood away from the heart. "We further validated the in vitro results in human arterial lesions and mouse models of arterial disorders, neither of which is solely regulated by IFNγ or IL-4, to provide clinically translatable evidence." (PMID 27796300, 2016).
Basal ganglia calcification (1 paper, 2017). The presence of calcium deposition affecting one or more structures of the basal ganglia. "Finally, increased expression of IFNγ in the CNS driven by a viral vector in mouse brain resulted in basal ganglia calcification and nigrostriatal degeneration, reminiscent of human idiopathic basal ganglia calcification (IBGC)." (PMID 28821274, 2017).
breast disease (1 paper, 2021). "Nonetheless, this suppression was circumvented in a mouse model of HER-2pos breast disease by supplying recombinant interferon-gamma to achieve a combination therapy significantly more potent than either agent." (PMID 33936816, 2021).
breast ductal carcinoma (1 paper, 2023). "At the protein level, via immunohistochemistry, a weak expression of CD274 and moderate expression of ferroptosis drivers (IFNG, TNFAIP3 and IDO1) were observed in biopsy of ductal breast carcinoma." (PMID 38201582, 2023). "The tumoral expression of CD274, TNFAIP3, IFNG and IDO1 in biopsy of breast ductal carcinoma was confirmed at the protein level via immunohistochemistry imaging." (PMID 38201582, 2023).
carcinoid syndrome (1 paper, 2022). "One patient had received everolimus and one patient interferon-gamma immunotherapy and telotristat for carcinoid syndrome." (PMID 35701566, 2022).
carotid atherosclerosis (1 paper, 2023). A thickening and loss of elasticity of the walls of carotid arteries that occur with formation of atherosclerotic plaques. "In subgroup comparisons, it was found that patients with progression of carotid atherosclerosis had a higher serum concentration of pentraxin 3 (11.4 pg/mL (6.70–13.9) versus 6.82 pg/mL (2.54–11.5) (p = 0.034)) and lower IFNγ (14.9 pg/mL (10.4–18.7) versus 20.8 pg/mL (14.8–25.3) (p = 0.008))." (PMID 37569579, 2023). "According to the results of univariate and multivariate Cox regression analysis, an increase in pentraxin 3 above certain cut-off values and a decrease in IFNγ below certain cut-off values did not significantly increase the RR of carotid atherosclerosis progression." (PMID 37569579, 2023).
cerebral (1 paper, 2023). "Systemically stimulating IFNγ signaling after middle cerebral artery occlusion, which could also stimulate migration, exacerbates ischemic damage." (PMID 37428916, 2023).
Childhood onset (1 paper, 2023). Onset of disease at the age of between 1 and 5 years. "Furthermore, childhood-onset SLE (cSLE) patients showed a high expression of IFNα and IFNγ as compared with controls, and IFNγ stimulation induced expression of T-bet in B cells." (PMID 38164134, 2023).
chronic conjunctivitis (1 paper, 2024). Conjunctivitis that is persistent and long-standing. "IFNγ is increased in chronic conjunctivitis, AKC, and VKC, and is a key cytokine in TH1 inflammation." (PMID 38999383, 2024).
chronic inflammatory demyelinating polyradiculoneuropathies (1 paper, 2010). "An autoimmune mechanism in IP is supported by higher levels of IFNγ in cases than in controls, as elevated IFNγ has been observed among persons experiencing acute or chronic inflammatory demyelinating polyradiculoneuropathies (AIDP or CIDP)." (PMID 20333310, 2010).
cocaine abuse (1 paper, 2012). Disorders related or resulting from use of cocaine. "Previous studies suggest that cocaine abuse may affect HIV pathogenesis by causing an imbalance of Th1-Th2 cytokines and stimulation of IFNγ responses and by upregulating HIV coreceptors, possibly by acting through σ-1 receptors." (PMID 22363505, 2012).
cognitive function (1 paper, 2020). "On the one side, these results can be interpreted as meaning that CD8+ Temrahi and CD8βhi T cells, together with high IFNγ-producing CD4+ T cells and the presence of HLA-B8, are immunological biomarkers associated with unhealthy aging (ie, impaired brain cognitive function)." (PMID 33324408, 2020).
colonic disease (1 paper, 2021). "As diseased colonic tissue, but not the unaffected duodenum, contained mainly CD4+ T cells with a prominent IFNγ-signature, we hypothesize that local microbial stimulation may have initiated colonic disease." (PMID 34226674, 2021).
craniopharyngioma (1 paper, 2023). A benign, partly cystic, epithelial tumor of the sellar region, presumably derived from Rathke pouch epithelium. "Notably, we observed upregulation of IFNγ, IL-1, IL-6, and TNFα in craniopharyngiomas, tumors difficult to resect due to their anatomical location and critical surrounding structures." (PMID 37492101, 2023).
cutaneous candidiasis (1 paper, 2024). Candidiasis of the skin manifested as eczema-like lesions of the interdigital spaces, perleche, or chronic paronychia. "Taken together, our study unravels a novel and as yet unrecognized detrimental role of TYK2 and IFNγ signaling in the immune defense against invasive cutaneous candidiasis and paves the way for exploring TYK2 inhibitors as potential treatment option." (PMID 39622833, 2024).
cystinosis (1 paper, 2019). Cystinosis is a metabolic disease characterized by an accumulation of cystine inside the lysosomes, causing damage in different organs and tissues, particularly in the kidneys and eyes. "Here, we explored if macrophage polarization to either proinflammatory M1-like M(LPS/IFNγ) or anti-inflammatory M2-like M(IL-4/IL-10) affected TNT-like protrusion formation, intercellular transport and, ultimately, the efficacy of cystinosis prevention." (PMID 31601865, 2019).
deficiencies (1 paper, 2025). "Additionally, PD-1 inhibition has been associated with increased production of pro-inflammatory cytokines, particularly interferon-gamma (IFN-gamma) and tumor necrosis factor-alpha (TNF-alpha), which can disrupt the function of pituitary cells and contribute to irreversible hormone deficiencies." (PMID 40416222, 2025).
diffuse midline glioma (1 paper, 2025). A diffuse glioma that arises from the midline structures of the central nervous system. "The upregulation of canonical interferon-gamma signaling has been correlated with GBM progression, and its expression within the tumor microenvironment plays a crucial role in overall survival, particularly in pediatric diffuse midline glioma (DMG) patients." (PMID 40842996, 2025).
eczema herpeticum (1 paper, 2016). "Genetic variants in IL-12 and IL-12RB, IFN-γ genes (IFNG) and IFNGR1 leading to partial IFNGR1 deficiency are related to AD in patients susceptible to eczema herpeticum." (PMID 27483258, 2016).
equine diseases (1 paper, 2024). "However, despite limitations, it is likely that SOCS1-KIR regulation of IFNγ, IP-10, and RANTES induced by LPS may have relevance in equine diseases." (PMID 39867889, 2024).
Facioscapulohumeral dystrophy (1 paper, 2023). Facioscapulohumeral muscular dystrophy (FSHD) is characterized by progressive muscle weakness with focal involvement of the facial, shoulder and limb muscles. "Mis-expression of DUX4 in skeletal muscle causes facioscapulohumeral dystrophy (FSHD), whereas expression in cancers suppresses IFNγ induction of major histocompatibility complex class I (MHC class I) and contributes to immune evasion." (PMID 37092726, 2023).
facioscapulohumeral muscular dystrophy (1 paper, 2014). An autosomal dominant disorder affecting the skeletal muscles of the face, scapula, and upper arm. "In support of this, elevated signal intensity in T2-STIR images was associated with increased immune and inflammatory cells (CD8+ T cells, IL12p40, IFNγ and TNFα) in facioscapulohumeral muscular dystrophy." (PMID 25203313, 2014).
fluorosis (1 paper, 2023). "The top 10 drugs have been reported in previous studies, namely Celastrol, LDN-193189, XPNPEP1, GNB5, Importazole, LDHB, NUAK1, IFNG, IFNB1, and YWHAH, suggesting that these drugs may be effective candidate drugs for the treatment of fluorosis." (PMID 36835629, 2023).
focal segmental glomerulosclerosis (1 paper, 2021). A renal disorder characterized by sclerotic lesions in the glomeruli. "Previous reports indicate that interferon gamma (IFN-γ), which is produced in response to HIV infection, is a potent inducer of APOL1 expression in vitro and that IFN-γ treatment can cause collapsing focal segmental glomerulosclerosis (FSGS) in humans with a high-risk APOL1 genotype." (PMID 34350953, 2021).
foot and mouth disease (1 paper, 2020). A viral infectious disease that results in infection in cattle and swine, has material basis in foot-and-mouth disease virus, which is transmitted by contaminated fomites, or transmitted by ingestion of food contaminated with infected meat or animal products. "(2009) showed that IFNγ, IL-10, and TNFa had peaked on week 3 in response to inactivated foot-and-mouth disease (FMD) vaccination while the remaining cytokines (IL-2, IL-4, IL-12p40) peaked on the 2nd week and decreased by the 3rd week." (PMID 33251155, 2020).
Gastrointestinal inflammation (1 paper, 2023). Inflammation of the alimentary part of the gastrointestinal system. "Similarly, increased amounts of various inflammatory mediators (e.g., interleukin [IL]-1β, IL-6, interferon gamma [IFN-γ], and tumor necrosis factor alpha [TNF-α]) in the stool samples of patients with PD indicate the presence of gastrointestinal inflammation." (PMID 38098067, 2023).
H syndrome (1 paper, 2021). A systemic inherited histiocytosis, with characteristic cutaneous findings accompanying systemic manifestations. "Moreover, H syndrome patients presented increased serum levels of IFNγ and GO enrichment of IFNγ-mediated signaling pathways." (PMID 33284430, 2021).
hearing loss (1 paper, 2024). "In the present study, we discovered for the first time that miR-409-3p is a target miRNA of IFNG in hearing loss." (PMID 39329776, 2024). "Notably, it identifies a noteworthy inverse relationship between IFNG and miRNA 409-3p levels, highlighting their potential roles in the pathogenesis of hearing loss." (PMID 39329776, 2024).
herpes labialis (1 paper, 2019). A lesion caused by type 1 or type 2 herpes simplex virus, typically involving the oralfacial region. "Our data are consistent with this in linking IFNG expression inversely with frequency of herpes labialis outbreaks." (PMID 30756512, 2019). "Higher IFNG and lower IL5 expression by PBMCs in the presence of HSV‐1 correlate with fewer herpes labialis outbreaks, and a single topical dose of SADBE to the arm of subjects with frequent herpes labialis episodes improves immune response to HSV‐1." (PMID 30756512, 2019). "Thus, SADBE treatment does not just partially reduce the defect in IFNG expression in those with frequent herpes labialis episodes, it completely reverses it." (PMID 30756512, 2019). "And the data show that a single dose of SADBE changes the immune response of subjects with frequent herpes labialis over 8 weeks to make it more like, and at least in IFNG expression better than, the immune response of subjects with few or no herpes labialis outbreaks." (PMID 30756512, 2019).
histiocytic neoplasm (1 paper, 2021). Histiocytic tumors are a heterogeneous group of tumors and tumorlike masses commonly associated with histologically identical extracranial lesions. "Furthermore, IFNγ has a role in MAPK activation, a pathway that has been successfully being targeted using MEK inhibitors, which have been shown to be efficacious in patients with histiocytic neoplasms." (PMID 33284430, 2021).
Hyperammonemia (1 paper, 2022). An increased concentration of ammonia in the blood. "Several studies confirmed that hyperammonemia activates the secretion of inflammatory cytokines (interleukin-6 (IL-6), interleukin-1beta (IL-1β), interferon gamma (IFN-γ), and tumor necrosis factor α (TNFα) in ammonia-induced astrocyte cultures." (PMID 35624703, 2022).
Hypothermia (1 paper, 2017). Reduced body temperature due to failed thermoregulation. "Hypothermia may thus be able to inhibit additional signals that are required for IFNγ production but leave IL-22 unaffected." (PMID 28706520, 2017).
idiopathic interstitial pneumonia (1 paper, 2005). A class of diffuse lung diseases that typically affect the pulmonary interstitium, although some also have a component affecting the airways (for instance, Cryptogenic organizing pneumonitis). "This increased level of IFNγ in NSIP, would be expected to counteract the postulated pro-fibrotic effect of IL-4 and may help explain the relative lack of fibrotic foci in this form of idiopathic interstitial pneumonia." (PMID 16287509, 2005).
in situ carcinoma (1 paper, 2007). A malignant epithelial neoplasm which is confined to the epithelial layer without evidence of further tissue invasion. "The optical density to IFNγ was higher in in situ carcinoma than in benign and infiltrating tumors." (PMID 17697357, 2007). "In in situ carcinomas we found an increased expression of both IFNγ and IFNγ-Rα." (PMID 17697357, 2007).
influenza A (H1N1) (1 paper, 2021). Viral infectious disease caused by the H1N1 strain of the influenza type A virus. "The present study also reported the lack of association between SNPs in the IL6, IFNG, IL17A, and TGFB genes and disease severity of Influenza A(H1N1)pdm09 virus infection." (PMID 34946862, 2021).
inner ear disease (1 paper, 2009). "The induction of IL1R2 by IL-4 certainly suggests that the maintenance of a TH2-like phenotype is important in controlling inner ear disease, whereas expression of IFNγ, that fosters a TH1-like response, has been observed in AIED patients, and blocks the expression of IL1R2." (PMID 19401759, 2009).
leukoplakia (1 paper, 2021). A white patch or plaque on a mucous membrane that cannot be characterized clinically or pathologically as any other disease. "However, IFNγ expression was significantly lower among the proliferative leukoplakia subgroup (log2 fold change −1.39, Padj < 0.05)." (PMID 36860910, 2021).
marginal zone lymphoma (1 paper, 2018). A usually indolent mature B-cell lymphoma, arising from the marginal zone of lymphoid tissues. "Th1 cells producing IFNγ have been shown to predominate in early extra-nodal marginal zone lymphoma." (PMID 29293620, 2018).
metastatic colon tumor (1 paper, 2016). "Collectively, miR-18a treatment promoted induction of M1 macrophages (F4/80+IFNγ+ and F4/80+IL-12+) with upregulated co-stimulatory factors such as CD80, and iNOS while inhibiting M2 macrophages (F4/80+TGFβ+, F4/80+IL-10+) in the liver of metastatic colon tumor bearing mice." (PMID 27028860, 2016).
microphthalmia (1 paper, 2010). Congenital or developmental anomaly in which the eyeballs are abnormally small. "Egwuagu and his associates also reported IFNγ transgenic mice had higher MHC class II expression in the eye, and the mice developed microphthalmia and microphakia." (PMID 20157617, 2010).
myonecrosis (1 paper, 2022). "IFNγ is also upregulated in degenerating mdx muscles, thus it was originally hypothesized that IFNγ could actively take part in myonecrosis, either directly or indirectly via its promotion of a pro-inflammatory environment in muscle." (PMID 36613804, 2022).
neutrophil leukemia (1 paper, 2023). "RNA-seq analysis of the Treg subpopulation from the murine CLL model revealed its unique phenotype characterized by upregulation of multiple factors, including Il10, Ifnγ, and the chemokines Ccl3/4/5 Cxcl13, which likely contribute to the neutrophil leukemia-supporting phenotype." (PMID 37817276, 2023).
obstructive sleep apnea (1 paper, 2024). "In this meta-analysis, we present the serum/plasma levels of tumor necrosis factor-alpha (TNF-α), interleukin (IL)-8, IL-1β, and interferon-gamma (IFN-γ) in both children and adults with obstructive sleep apnea (OSA) in comparison to controls." (PMID 38592305, 2024).
oropharyngeal tumors (1 paper, 2019). "In addition, when only considering the oropharynx, the expression of the IFNγ gene was significantly higher in HPV+ samples compared to HPV− oropharyngeal tumors." (PMID 31394808, 2019).
Paralysis (1 paper, 2018). Paralysis of voluntary muscles means loss of contraction due to interruption of one or more motor pathways from the brain to the muscle fibers. "Treatment with CBD caused attenuation of EAE disease paradigms as indicated by a significant reduction in clinical scores of paralysis, decreased T cell infiltration in the central nervous system, and reduced levels of IL-17 and IFNγ." (PMID 30123217, 2018).
pasteurellosis (1 paper, 2021). Infections with bacteria of the genus pasteurella. "In lambs naturally infected with pneumonic pasteurellosis, the association between measured proinflammatory cytokines and clinical sum score demonstrated a positive correlation with interleukin-6 and interferon gamma." (PMID 34944151, 2021). "The correlation between assessed proinflammatory cytokines and CIIS in lambs naturally infected by pneumonic pasteurellosis revealed a positive correlation between CIIS and IL-6 and IFNγ, while other estimated proinflammatory cytokines exhibited a negative correlation with CIIS." (PMID 34944151, 2021).
placental insufficiency (1 paper, 2012). Failure of the placenta to deliver an adequate supply of nutrients and oxygen to the fetus. "This is in contrast to our observation that IFNγ is produced at higher concentrations by PBMC from women with IUGR with placental insufficiency." (PMID 22110537, 2012). "The higher ratios and the higher levels of IL-8, IFNγ, and TNFα are suggestive of a higher proinflammatory bias in IUGR with placental insufficiency than in normal pregnancy." (PMID 22110537, 2012). "The levels of the proinflammatory cytokines IL-8 (1803 pg/mL ± 89, P < 0.001), IFNγ (126 pg/mL ± 33, P < 0.02), and TNFα (340 pg/mL ± 46, P < 0.04) are significantly higher in IUGR with placental insufficiency as compared to normal pregnancy (1049 pg/mL ± 45, 18 pg/mL ± 6, 70 pg/mL ± 21, resp)." (PMID 22110537, 2012). "IL-8, IFNγ, and TNFα were higher in IUGR with placental insufficiency than in normal pregnancy." (PMID 22110537, 2012). "In addition to the higher production of IL-8 by PBMC from women with IUGR, the proinflammatory cytokines IFNγ and TNFα are also produced at higher levels in IUGR with placental insufficiency versus normal pregnancy." (PMID 22110537, 2012). "However, the IFNγ/IL-10 ratio was actually higher in normal pregnancy than in IUGR without placental insufficiency (P < 0.03)." (PMID 22110537, 2012).
poliovirus infection (1 paper, 2019). An disease or disorder caused by infection with Enterovirus C. "However, clearance of poliovirus infection by both CD4+ve and CD8+ve cytotoxic T lymphocytes by secretion of IFNγ has been shown by some earlier studies." (PMID 31396204, 2019).
polycystic kidney disease (1 paper, 2016). A usually autosomal dominant and less frequently autosomal recessive genetic disorder characterized by the presence of numerous cysts in the kidneys leading to end-stage renal failure. "While ablation of IFNγ prevents the neonatal disease seen in Socs1-/- mice, mice lacking both SOCS1 and IFNγ nevertheless succumb in adult life to polycystic kidney disease and/or a range of inflammatory lesions." (PMID 27583437, 2016).